KRT28 (keratin 28)
Description:
Essential for the proper assembly of types I and II keratin protein complexes and the formation of keratin intermediate filaments in the inner root sheath (irs).
Synonyms: KRT25D; K25IRS4
Tractability: No criterion of Open Targets' tractability assessment is met for any kind of drug.
Gene: Protein-coding gene on chromosome 17 (40,792,196 to 40,799,959, reverse strand). Ensembl gene ENSG00000173908.
Subcellular location: Cytoplasm
Pathways (Reactome):
Developmental Biology: Formation of the cornified envelope; Keratinization
Gene Ontology:
Molecular function: protein binding; structural constituent of skin epidermis; structural molecule activity
Biological process: epithelial cell differentiation; hair follicle morphogenesis; intermediate filament organization; morphogenesis of an epithelium
Cellular component: extracellular exosome; cytoplasm; cytoskeleton; cytosol; keratin filament
Genetic constraint (gnomAD): Loss-of-function variants: 38 observed, 41.61 expected, observed/expected ratio (o/e) 0.91, 90% interval 0.7 to 1.2. The upper end of that interval is the gene's LOEUF score, 1.2, which puts it in group 5 of 6, group 1 being the genes least tolerant of losing a copy. Missense variants: 508 observed, 541.3 expected, observed/expected ratio (o/e) 0.94, 90% interval 0.87 to 1.01. Synonymous variants: 201 observed, 210.6 expected, observed/expected ratio (o/e) 0.95, 90% interval 0.85 to 1.07.
Homologues: Orthologues: chimpanzee KRT28 (99% identical), macaque KRT28 (97% identical), dog KRT28 (89% identical), rabbit KRT28 (86% identical), pig KRT28 (86% identical), mouse Krt28 (85% identical), rat Krt28 (85% identical), guinea pig KRT28 (81% identical). Paralogues in human: KRT27 (77% identical), KRT25 (72% identical), KRT26 (68% identical), KRT10 (57% identical), KRT24 (53% identical), KRT14 (50% identical), KRT12 (49% identical), KRT15 (49% identical), KRT16 (49% identical), KRT17 (48% identical), KRT13 (45% identical), KRT19 (43% identical), and 56 more.
Diseases named in the same sentence as KRT28 in open-access papers:
KRT28 is named in the same sentence as 2 diseases in open-access papers, as found by Europe PMC text mining. Sharing a sentence is not in itself a finding about the gene and the disease. The quoted sentences say what the papers report.
cardiac arrhythmia (1 paper, 2023). Any disturbances of the normal rhythmic beating of the heart or MYOCARDIAL CONTRACTION. "Based on the functional analyses, other phenotypes (blood pressure and cardiac arrhythmia for AGTR1) and biological pathways (keratinization and cornified envelope for KRT28) related to CKD were also identified." (PMID 37210443, 2023).
KRT28 also shares sentences with these, for which no sentence is quoted: cancer (1 paper).